IDH2 (isocitrate dehydrogenase (NADP(+)) 2)
Diseases named in the same sentence as IDH2 in open-access papers (continued):
Sharing a sentence is not in itself a finding about the gene and the disease.
glioma (continued). "However, for patients younger than 55 years, or those with a history of lower-grade glioma and/or tumors showing immunohistochemical loss of nuclear ATRX expression, negative IDH1 p.R132H immunostaining should be followed by DNA sequencing to identify less common IDH1 or IDH2 mutations." (PMID 40141375, 2025). "The INDIGO trial, a phase 3 study involving 331 patients with residual or recurrent grade 2 IDH-mutant gliomas, demonstrated the efficacy of vorasidenib, an oral, brain-penetrant inhibitor of mutant IDH1 and IDH2." (PMID 39439623, 2024). "Extracted DNA from two FFPE glioma samples, IDH1 p.R132H with VAF of 39.5% and IDH2 p.R172K with VAF 48.9% (Sample 22), were diluted with DNA extracted from IDH1/2 wild-type FFPE glioma sample." (PMID 38796421, 2024). "Around 80% of grade II and III astrocytomas, oligodendrogliomas, secondary GBM, and tumors that develop from lower-grade gliomas exhibit alterations in the genes responsible for IDH1 or, less frequently, IDH2." (PMID 38686271, 2024). "Pediatric infratentorial IDH-mutant glioma needs to be included in differential diagnosis, and differentiation is possible after testing for IDH1 and IDH2 sequencing." (PMID 39440342, 2024). "Over 90% of IDH1/2 mutant gliomas harbor the IDH1 p.R132H alteration while IDH1 p.R132C/G/L/S and IDH2 p.R172G/K/M are more rarely observed." (PMID 38796421, 2024). "Several studies suggest that mutations of isocitrate dehydrogenases (IDH1/2), which represent one of the main characteristics of glioma cells and occur at specific codons in IDH1 and IDH2, are attractive candidates for glioma immunotherapy." (PMID 38274827, 2023). "Although a recent clinical trial reported that an inhibitor targeting mutant IDH1 and IDH2 induced durable therapeutic efficacy in lowgrade glioma, the impact of directly targeting mutant IDH for high-grade glioma is under clinical investigation." (PMID 38012788, 2023). "In the present study, we used multiple newly implemented techniques to investigate some of the genetic alterations in IDH1, IDH2, CDKN2A, MYB and MYBL1 in pediatric low-grade gliomas." (PMID 35574540, 2022). "The detection of IDH1R132 and IDH2R140/R172 mutations is helpful information to guide the diagnosis of several malignancies such as glioblastomas, gliomas, AITL, MDS, or AML and identify patients eligible for anti‐IDH1 and/or anti‐IDH2 targeted therapies." (PMID 36062346, 2022). "In gliomas, increased hBCATc and hBCATm expression has been limited to gliomas with wild-type isocitrate dehydrogenase 1 (IDH1), cytosolic and IDH2, mitochondrial." (PMID 33367952, 2021). "Cells from mouse PDXs of mutIDH1 glioma have been shown to have significantly higher mitochondrial density than corresponding WT IDH1 cells, an interesting observation given that IDH2 localizes to mitochondria." (PMID 35028610, 2021). "Genetic alterations in IDH1 or IDH2, TERT, and co-deletion of chromosome arms 1p and 19q (1p/19q codel) were rather found in low grade gliomas (LGG; grades II-III)." (PMID 33154756, 2020).
glioma (continued). "Currently, D-2-HG is being used as a biomarker to monitor the disease progression, and mutants IDH1/IDH2-specific inhibitors are in clinical trials for AML and glioma." (PMID 31900386, 2020). "Since IDH1/2 mutants enzyme inhibitors have good application prospects in pre-clinical research and clinical trials of glioma, we believe that IDH1/IDH2 mutant enzyme inhibitors will bring new hope to glioma patients." (PMID 31263678, 2019). "Clinical trials are also underway to target mutant IDH1 and IDH2 in AML, gliomas, myelodysplastic syndrome, and other solid tumors." (PMID 28653623, 2017). "We then compared the whole-transcriptome sequencing expression profiles of the IDH2 mutant and IDH1/2 wild-type gliomas." (PMID 27245697, 2016). "To investigate the different clinical and molecular characterization between IDH1 mutant and IDH2 mutant gliomas, we studied a cohort of 811 patients consisting 448 IDH1 mutant, 18 IDH2 mutant and 345 IDH1/2 wild-type gliomas." (PMID 27245697, 2016). "A subset of leukemia cells with mutations in the metabolic enzymes isocitrate dehydrogenase 1 (IDH1) and 2 (IDH2), and IDH1-mutant glioma cells have been shown to be particularly sensitive to glutaminase inhibition." (PMID 27806325, 2016). "First, we used a Gene Set Enrichment Analysis (GSEA) to compare the global gene expression profiles of the IDH2 mutant and IDH1 mutant gliomas." (PMID 27245697, 2016). "No mutations of IDH3, which normally catalyse the same reaction as IDH1/IDH2 (but use NAD+ as substrate) have been noted in gliomas, so the consequence of its downregulation can only be extrapolated from reports on IDH1/IDH2." (PMID 24728830, 2014). "Six glioma cases possessed a mutant IDH1 or a mutant IDH2, and 12 cases had wild-type IDH1 and IDH2." (PMID 23456655, 2013). "Initially, the production of d-2-hydroxyglutarate in gliomas, secondary glioblastomas, and AML by mutant IDH2 results in a decrease of 2OG and hence depletion of succinate, fumarate, and malate from the rest of the Krebs cycle." (PMID 22675360, 2012). "It recruited 52 adult patients with recurrent or refractory grade 2–4 IDH1- or IDH2-mutant glioma (22 non-enhancing and 30 enhancing), from 2015 to 2017." (PMID 40867259, 2025). "The minimal alterations in IDH2 align with previous findings, indicating that IDH mutations are more commonly associated with lower-grade gliomas rather than glioblastoma." (PMID 40282990, 2025). "Isocitrate dehydrogenase is a metabolic enzyme found in glioma and non-nervous system tumors that has five isotypes, with IDH-1 and IDH-2 comprising most mutations in glioblastoma." (PMID 40422257, 2025). "The prognosis of gliomas is significantly affected by these molecular alterations, such as whether IDH1, IDH2, EGFR, CDKN2A, and CDKN2B are altered for adult‐type gliomas, and whether H3 K27 and H3 G34 are altered for pediatric‐type gliomas." (PMID 39804195, 2025). "Based on the data described herein, we hypothesize that the samples characterized by elevated xCT expression (WT-12, IDH-2, IDH-3, and DA-1) may be resistant to ferroptosis-inducing therapies and be characterized by elevated glioma uptake of [18F]hGTS13." (PMID 39776801, 2025). "A recent meta-analysis suggested that IDH1 and IDH2 mutations are significantly associated with an increased incidence of preoperative seizures in low-grade (II) but not in high-grade (III and IV) gliomas." (PMID 40103938, 2025). "A phase III clinical trial of an IDH1 and IDH2 inhibitor vorasidenib yielded promising results among patients with low-grade IDH-mutant gliomas who had undergone initial surgery and no radiation or chemotherapy." (PMID 38931350, 2024). "Additionally, vorasidenib, an IDH1/IDH2 inhibitor, has shown efficacy in extending progression-free survival in patients with IDH-mutant gliomas, providing an opportunity to delay treatments like radiation and chemotherapy, thus preserving cognitive function." (PMID 39439623, 2024).
glioma (continued). "A stereotactic brain biopsy and subsequent neuropathological evaluations were performed, resulting in a glioma tumor isocitrate dehydrogenase 1 (IDH-1) and 2 (IDH-2) wild type, glial fibrillary acidic protein (GFAP) and oligodendrocyte transcription factor 2 (Olig2) positive." (PMID 37692853, 2023). "The dual IDH1/IDH2 inhibitor vorasidenib exhibited better brain permeability and target engagement than ivosidenib in a pilot perioperative randomized clinical trial in patients with IDH1-mutant glioma." (PMID 36823302, 2023). "Histologically it is characterized as a diffusely infiltrating glioma with mitotic activity, showing no mutations in IDH1, IDH2 or H3-genes." (PMID 37561227, 2023). "It is well known that wild-type isocitrate dehydrogenase 1 and 2 (IDH1 and IDH2, hereafter collectively referred to as IDH) and 1p19q non-deletion are two important genetic events in gliomas closely associated with rapid progression and high recurrence." (PMID 36969175, 2023). "In gliomas, its occurrence seems to be independent of IDH1/IDH2 somatic mutations, while an inverse correlation with EGFR amplification has been suggested, but not confirmed, in an independent validation series." (PMID 36011350, 2022). "Thus, the analysis of genomic alterations such as the isocitrate dehydrogenase 1 and 2 (IDH1, IDH2) and the histone H3 family 3A (H3F3A), HIST1H3B, and HIST1H3C genes as well as analysis of 1p and 19q status are now integrated aspects of glioma classification." (PMID 35453544, 2022). "In order to identify the underlying mechanisms that drive the development and progression of IDH wild-type glioma, here we performed scRNA-seq analysis of one surgically resected of glioma tumor without IDH1 and IDH2 mutations." (PMID 34805184, 2021). "IDH1 and IDH2 are promising molecular targets for precision therapy not only in gliomas but also in other malignancies." (PMID 35996504, 2021). "In glioma, non-canonical (i.e. not IDH1 R132H or IDH2 R170C) IDH1 variants have different clinical characteristics and tend to arise in different locations in the brain compared with the canonical variants." (PMID 34854890, 2021). "The IDH-wildtype astrocytic glioma classified as low-grade glioma MYB/MYBL1 by methylation profiling, was negative for IDH1/IDH2 and BRAF mutations by sequencing analysis and was 1p/19q non-codeleted." (PMID 33941250, 2021). "Moreover, the results showed that glioma-related mutant genes included MGMT (n = 14), IDH1 (n = 8), IDH2 (n = 1), 1p/19q (n = 3), and BRAF (n = 2)." (PMID 32973641, 2020). "In addition, AG-881 is a promising orally available dual inhibitor of mutant IDH1 and mutant IDH2 that was in Phase I/II clinical trial until this year, recruiting AML patients with mutant IDH1/2, as well as glioma patients (NCT02492737 and NCT02481154)." (PMID 32548570, 2020). "Interestingly, we found both IDH1/2 genes mostly prevalent in two subtypes of gliomas: astrocytoma and oligodendrogliomas with a frequency of 71.4 and 85.7% for IDH1 and 14.28 and 28.5% for IDH2, respectively." (PMID 33552543, 2020).
glioma (continued). "On the contrary, IDH2 mutational pattern and MGMT methylation status showed comparable frequency in both methylated and unmethylated MGMT gene for same series of glioma patients and therefore, did not correlate significantly (p > 0.05)." (PMID 33552543, 2020). "A similarly designed trial of Enasidenib in IDH2-mutant solid tumors, including glioma, was completed in 2016, but data from the trial has not yet been published (ClinicalTrials.gov NCT02273739)." (PMID 31165048, 2019). "In the same year, a trial of AG-221 in IDH2-mutant malignancies, including gliomas, was completed, but results have not yet been reported (ClinicalTrials.gov NCT02273739)." (PMID 31652645, 2019). "This indicates that, unlike the observations in gliomas, IDH1 or IDH2 mutations in chondrosarcoma do not correlate with radiosensitivity." (PMID 31160965, 2019). "Accordingly, the Food and Drug Administration (FDA) has approved the mutant IDH1 inhibitor, ivosidenib, and IDH2 inhibitor, enasidenib for adults with relapsed or refractory acute myeloid leukemia, inhibitors of mutant IDH have entered clinical trials for glioma treatment." (PMID 30625996, 2019). "To determine whether IDH2 mutant cell lines would also demonstrate a similar response, we created two cell lines using the WT IDH LN18 glioma as parental, to either express IDH1 R132H or IDH2 R172K." (PMID 29562167, 2018). "Mutations in isocitrate dehydrogenase 1 (IDH1), and less frequently in IDH2, occur in 80% of grade II and grade III astrocytomas and oligodendrogliomas, and are also found in high-grade glioblastomas that have arisen over time from these lower-grade gliomas." (PMID 29759978, 2018). "This conclusion is strongly supported by the observation that isocitrate dehydrogenase (IDH1 and IDH2) mutations are present in the majority of WHO II and III gliomas and secondary glioblastomas, but not in primary glioblastomas." (PMID 30279357, 2018). "In contrast, expression levels of enzymes involved in downstream metabolism of isocitrate, including IDH1, IDH2 and IDH3A, α-KGDH, succinate dehydrogenase (SDHB), fumarate hydratase (FH) and malate dehydrogenase (MDH2), were remarkably lower in IDH1MUT glioma versus IDH1WT glioma." (PMID 28467784, 2017). "Patients with IDH2 mutant gliomas exhibited longer Overall survival (OS) (p < 0.05) and longer Progression-free survival (PFS) (p < 0.05) than patients with IDH1/2 wild-type gliomas." (PMID 27245697, 2016). "Glioma development is frequently associated with mutations of the isocitrate dehydrogenase IDH1 and IDH2 genes, whereas mutations of IDH3 have never been observed in GBM." (PMID 25050814, 2014). "One could also capture additional glioma-relevant genes like IDH1 and IDH2 by adding probes targeting these genomic regions." (PMID 25608559, 2014). "We found that NADP+-dependent isocitrate conversion was not decreased in E478 xenografts as compared to IDHwt glioma, indicating that cells compensate for loss of IDH1 activity by increasing mitochondrial IDH2 activity by inducing mitochondrial biosynthesis." (PMID 24252742, 2013). "We therefore analysed IDH1 and IDH2 statusat codon 132 of IDH1 and codon 172 of IDH2 by direct sequencing and anti-IDH1-R132H immunohistochemistry in 53 paired samples and their recurrences, including 29 low- grade gliomas, 16 anaplastic gliomas and 8 Glioblastomas." (PMID 23840696, 2013). "In this study, we have demonstrated that promoter hypermethylation of IDH1 and IDH2 genes is absent or very rare in human gliomas and other brain tumors." (PMID 23267435, 2012). "IDH2 levels were not significantly upregulated in glioma samples." (PMID 41034696, 2025).
glioma (continued). "Indeed, total IDH1 (IDH1wt and IDH1R132H) protein levels were higher in mIDH cell lines when compared to wtIDH cells and IDH1 and IDH2 expression was highest in PDGFRA+ tumor cells, which are the majority of glioma cells in mIDH tumors and a small percentage of GSCs in wtIDH tumors." (PMID 40060572, 2025). "However, oligodendroglioma is defined by the co-occurrence of mutations in the IDH1 or IDH2 genes and 1p/19q codeletion, which are absent in F3T3 gliomas." (PMID 38730596, 2024). "Low-grade gliomas in children rarely transform into high-grade tumors, unlike adult gliomas, in which the presence of the IDH1 and IDH2 mutations may influence the development of high-grade gliomas." (PMID 38612890, 2024). "Additionally, since IDH2-mutant glioma xenograft model is lacking, translational insight is scant to date." (PMID 38012788, 2023). "One should be aware that tumors classified in the past as GBM may carry an IDH1/IDH2 mutation or exhibit a G-CIMP phenotype (with or without an IDH1/IDH2 mutation), both of which are prognostic factors for longer survival in glioma patients." (PMID 37999122, 2023). "For instance, low-grade gliomas have been classified according to the 1p and 19q loci co-deletion as well as the mutations in the IDH1 and IDH2 genes; tumors without these alterations have been shown to be clinically and molecularly similar to high-grade tumors." (PMID 34868236, 2021). "Finally, driver gene analysis of the immune types revealed that IDH1, IDH2, and PLCH2 are the major driver genes for glioma, clearly suggesting that they may be potential targets for mRNA vaccines." (PMID 34603319, 2021). "In contrast, differential IDH2 status revealed no variation with respect to OS of glioma cases." (PMID 33552543, 2020). "However, IDH2/R140, unlike IDH1/R132 and IDH2/R172 mutations, is not found in gliomas, cholangiocarcinomas, and chondrosarcomas." (PMID 31817761, 2019). "Also of interest, is that a number of common mutations found in some classes of human glial tumors are absent in our PXA cohort, including mutations in IDH1 and IDH2 and that BRAF is not duplicated in PXA." (PMID 21479234, 2011). "In a cohort of 43 pediatric patients with newly diagnosed WHO grade 3 or 4 gliomas treated on the Children’s Oncology Group ACNS0423 study, IDH1 mutations were detected in 7 of 43 (16.3%) of children with primary malignant gliomas, and no IDH2 mutations were identified." (PMID 39876890, 2024). "In this study, we examined the use of whole-genome DNA methylation array (WGMA) testing to identify IDH1/IDH2 pathway disruption, through the detection of CIMP, in addition to the characterization of additional molecular alterations that may assist in the classification of glioma tumors." (PMID 36360312, 2022). "This cohort assessed 84 tumours across the three grade 2–3 glioma genotypes according to WHO 2016 and did not have data on IDH2 status." (PMID 37316586, 2023). "In this study, we found that the mutant genes in the metastatic brain tumors included ALK, MDM2, ATM, BRCA1, FGFR1, and KRAS, and there were no glioma-related mutant genes (MGMT, IDH1, IDH2, 1p/19q, BRAF, and TERT)." (PMID 32973641, 2020).